RN7SKP299 (RN7SK pseudogene 299)
Gene: Miscellaneous RNA gene on chromosome 6 (136,545,192 to 136,545,492, forward strand). Ensembl gene ENSG00000271765.
Homologues: Orthologues: chimpanzee 7SK (99% identical), mouse Gm54520 (44% identical), mouse Gm54492 (44% identical), mouse Gm54510 (41% identical), guinea pig 7SK (41% identical), mouse Gm54500 (37% identical), guinea pig 7SK (32% identical). Paralogues in human: RN7SKP226 (56% identical), RN7SKP9 (56% identical), RN7SKP124 (56% identical), RN7SKP193 (56% identical), RN7SKP128 (55% identical), RN7SKP69 (55% identical), RN7SKP151 (55% identical), RN7SKP25 (55% identical), RN7SKP6 (55% identical), RN7SKP78 (54% identical), 7SK (54% identical), RN7SKP160 (54% identical), and 284 more.